TMEM11 (transmembrane protein 11)
Description:
Plays a role in mitochondrial morphogenesis.
Synonyms: C17orf35; PM1; PMI
Tractability: Antibody: UniProt predicts a signal peptide or a membrane-spanning region. PROTAC: ubiquitination databases record sites on it; its protein half-life has been measured.
Gene: Protein-coding gene on chromosome 17 (21,197,954 to 21,214,595, reverse strand). Ensembl gene ENSG00000178307.
Subcellular location: Mitochondrion inner membrane
Subcellular location (Human Protein Atlas): Mitochondria
Pathways (Reactome):
Organelle biogenesis and maintenance: Cristae formation
Gene Ontology:
Molecular function: protein binding
Biological process: mitochondrion organization; inner mitochondrial membrane organization
Cellular component: mitochondrial inner membrane; mitochondrion; plasma membrane
Genetic constraint (gnomAD): Loss-of-function variants: 1 observed, 17.67 expected, observed/expected ratio (o/e) 0.0566, 90% interval 0.019 to 0.27. The upper end of that interval is the gene's LOEUF score, 0.27, which puts it in group 1 of 6, group 1 being the genes least tolerant of losing a copy. Missense variants: 172 observed, 264.02 expected, observed/expected ratio (o/e) 0.65, 90% interval 0.57 to 0.74. Synonymous variants: 122 observed, 123.5 expected, observed/expected ratio (o/e) 0.99, 90% interval 0.85 to 1.15.
Homologues: Orthologues: chimpanzee TMEM11 (100% identical), dog TMEM11 (99% identical), guinea pig TMEM11 (99% identical), macaque TMEM11 (99% identical), mouse Tmem11 (96% identical), rat Tmem11 (91% identical), rabbit TMEM11 (90% identical), pig TMEM11 (88% identical), tropical clawed frog natd1 (86% identical), zebrafish tmem11 (81% identical), Drosophila melanogaster Pmi (39% identical).
Diseases named in the same sentence as TMEM11 in open-access papers:
TMEM11 is named in the same sentence as 13 diseases in open-access papers, as found by Europe PMC text mining. Sharing a sentence is not in itself a finding about the gene and the disease. The quoted sentences say what the papers report.
cancer (3 papers, 2023 to 2025). A tumor composed of atypical neoplastic, often pleomorphic cells that invade other tissues. "While limited evidence indicates the contributions of LFA-1, CD11c+ DC, and TMEM11+ microglia to immune tolerance, their involvement in the immune evasion of cancer remains unknown (see Discussion for details)." (PMID 37835514, 2023).
TMEM11 also shares sentences with these, for which no sentence is quoted: tumor (5 papers); Hearing Loss (2); infection (2); scleroderma (2); Autoimmunity (1); Hypercholesterolemia (1); Hypoalbuminemia (1); Larsen syndrome (1); Nephropathy (1); osteosarcoma (1); polymyositis (1); psoriatic arthritis (1).